CD276 (CD276 molecule)
Diseases named in the same sentence as CD276 in open-access papers (continued):
Sharing a sentence is not in itself a finding about the gene and the disease.
breast cancer (147 papers, 2013 to 2026). A primary or metastatic malignant neoplasm involving the breast. "CD276 has been reported to be significantly negatively associated with immune infiltration of CD8+ T cells in breast cancer." (PMID 40657358, 2025). "Our group has previously investigated several tumor-associated target in cancer, such as CD22 in breast cancer and esophageal cancer, CD276 in esophageal cancer." (PMID 41573636, 2025). "CD276 is an immunoregulatory protein that inhibits T-cell activation, is overexpressed in breast cancer, and is associated with metastasis and advanced disease." (PMID 29050362, 2017). "Meanwhile, breast cancer, ovarian cancer, and colon cancer also exhibited higher levels of the CD276 protein phosphorylated at residue S525." (PMID 39766794, 2024). "The expression of B7 homolog 3 (B7-H3; CD276-encoded) differs significantly in breast cancer patients according to race and is lowest in Black women, whereas the expression of CD8, CD25, CD56, CD127, EpCAM, ER, and Ki-67 correlates with survival prognosis." (PMID 37744276, 2023). "The type I transmembrane protein B7-H3, also called CD276, is highly expressed in various solid tumors, such as prostate cancer, renal cell carcinoma, non-small cell lung cancer, and breast cancer, but expressed at low levels in normal human tissues." (PMID 37149721, 2023). "Superior anti-tumor efficacy of CD28 HD/TM was also reported in HER2-positive breast cancer and CD276-positive neuroblastoma." (PMID 37924157, 2023). "Beginning with in vitro testing against the HER2+/CD276+ JIMT-1 (JIMT) and the HER2−/CD276+ DU4475 breast cancer cell lines, we found that both ADCs exhibited potent activity against the double-positive cells." (PMID 38019654, 2023). "For example, CD276+ neuroblastoma and breast cancers were generally much more sensitive to the ADC than CD276+ pancreatic cancers and glioblastomas." (PMID 38019654, 2023). "To determine the clinical relevance of CD147 and CD276 co-expression in BC, we analyzed their expression profiles using the Molecular Taxonomy of Breast Cancer International Consortium (METABRIC) database." (PMID 37648771, 2023). "Lastly, we performed survival analyses using breast cancer datasets for the CD276/B7H3 (probe ID 224859_at) subtype of TNBC." (PMID 36550153, 2022). "As a recently discovered member of the B7 family, B7-H3 (also known as CD276) exhibits a dual role in immune cell responses and has been found to be upregulated in a variety of cancer types, such as colorectal and breast cancers." (PMID 35585975, 2022). "Previously, we reported CD200 and CD276, respectively, as candidate innate and adaptive immune checkpoints in breast cancer stem cells." (PMID 36494785, 2022). "In overall samples, CD276/B7H3 mRNA expression was higher in breast cancers of AA patients compared to CA patients." (PMID 36550153, 2022). "CD200 and CD276 are candidate inhibitory immune checkpoints in breast cancer stem cells, which are potentially regulated by Wnt, TGF‐β, and Hedgehog signaling." (PMID 33932112, 2021). "More than 70% of colorectal, prostate, ovarian, pancreatic and breast cancer specimens show expression of CD276 (B7–H3), a potential immune checkpoint family member." (PMID 34290311, 2021). "Following the principle, our study revealed CD200 and CD276 as candidate immune checkpoints in breast cancer stem cells." (PMID 33932112, 2021). "Taken together, we considered CD200 and CD276, respectively, as potential innate and adaptive immune checkpoints in breast cancer stem cells." (PMID 33932112, 2021). "Our study suggested that CD200 and CD276 are candidate inhibitory immune checkpoints in breast cancer stem cells, which are potentially regulated by Wnt, TGF‐β, and Hedgehog signaling." (PMID 33932112, 2021). "In this study, we identified CD200 and CD276, respectively, as candidate innate and adaptive immune checkpoints in breast cancer stem cells." (PMID 33932112, 2021).
breast cancer (continued). "Of note, levels of CD200 and CD276 expression were higher in TGF‐β dominant breast cancer than in other immune types of breast cancer." (PMID 33932112, 2021). "Similar to VTCN1, CD276 is mainly expressed on tumor cells, such as lung cancer, renal cell carcinoma, breast cancer, endometrial cancer, and ovarian cancer cells." (PMID 34367975, 2021). "We also identified gene signatures that represent Wnt, TGF‐β, and Hedgehog signaling‐related CD200 and CD276 expression in breast cancer stem cells." (PMID 33932112, 2021). "Enrichment of CD276 expression increased stemness of breast cancer cell lines by activation of the MAPK kinase pathway." (PMID 33932112, 2021). "The innate immune checkpoint CD200 and the adaptive immune checkpoint CD276, respectively, exhibited a strong correlation with basal/stem gene signature and invasiveness gene signature, both of which represent breast cancer stem cells." (PMID 33932112, 2021). "In breast cancer cells, it was shown that miR-708-5p not only targeted CD276, an immune checkpoint molecule, but also decreased phosphorylated signal transducer and activator of transcription 3 (pSTAT3) levels." (PMID 29050362, 2017). "In melanoma and breast cancer, CD276 has been reported to promote metastasis and chemoresistance through regulating JAK2/STAT3 signaling pathways and promoting the expression of cytokines and other metastasis-associated genes." (PMID 27329595, 2016). "Previous studies have demonstrated that B7-H3/CD276 primarily exerted a co-inhibitory function in tumor immunity and was overexpressed in various malignancies, including NSCLC and breast cancer, where it was closely associated with immune evasion by tumor cells." (PMID 40953006, 2025). "Recently, numerous studies have shown that the expression of CD276 in prostate cancer, breast cancer, and other tumors is significantly up-regulated, and it is directly associated with tumor avoidance of the host immune response and the poor prognosis of these patients." (PMID 39766794, 2024). "Moreover, we investigated the clinical relevance of CD147 and CD276 co-expression in HER2+ breast cancer (BC) and triple-negative breast cancer patients who underwent chemotherapy." (PMID 37648771, 2023). "Similarly, CD276-positive cell lines derived from pancreatic tumors tended to be relatively resistant, whereas those from breast cancers, colon cancers, lung cancers, and pediatric Ewing’s sarcoma were hypersensitive." (PMID 38019654, 2023). "Numerous studies have revealed that CD276 is overexpressed in a variety of tumors, including leukemia, breast cancer, prostate cancer, and other tumors, with expression levels strongly correlating with poor patient prognosis, and presumably involved in tumor immune evasion." (PMID 35211173, 2022). "Finally, a metabolic imaging experiment further confirmed that CD276 enhances the glucose uptake by tumor cells, thereby promoting tumor growth in a mouse breast cancer xenograft model." (PMID 33842369, 2021). "In summary, our study revealed that CD200 and CD276 may act as cancer stem cell–specific immune checkpoints to mediate immune resistance in breast cancer." (PMID 33932112, 2021). "Synergistic inhibition of stemness‐related pathways including Wnt, TGF‐β, and Hedgehog signaling may improve the efficacy of ICB treatment targeting CD200 or CD276 in breast cancer stem cells." (PMID 33932112, 2021). "Therefore, Wnt, TGF‐β, and Hedgehog signaling are potentially the main pathways regulating the inhibitory immune checkpoints CD200 and CD276 in breast cancer stem cells." (PMID 33932112, 2021). "CD276 is widely observed in vascular endothelial cells of colon, lung, and breast cancers." (PMID 33842369, 2021). "A similar strategy may be adopted in breast cancer; low expression of CD276 enhances cancer cell sensitivity to paclitaxel treatment and AKT/mTOR inhibitors." (PMID 34367975, 2021).
breast cancer (continued). "Our results suggested that cancer stem cell–specific CD200 and CD276 might inhibit the surveillance of innate and adaptive immune system in luminal A breast cancer, thus contributing to poor survival." (PMID 33932112, 2021). "Moreover, we identified gene signatures that represent Wnt, TGF‐β, and Hedgehog signaling‐related CD200 and CD276 expression in breast cancer stem cells." (PMID 33932112, 2021). "Furthermore, in addition to the advanced colorectal and breast cancers, CD276-positive circulating endothelial cells also occur in higher frequencies in patients with GBM." (PMID 31075138, 2019). "Therefore, it is difficult to conclude what effect miR-708-5p suppression of CD276 has on breast cancer cells." (PMID 29050362, 2017). "In this study, the strong association of TGF‐β signaling with the cancer stem cell–specific immune checkpoints implies that inhibition of TGF‐β signaling may impede CD200‐ or CD276‐mediated immune evasion of breast cancer stem cells, which has rarely been described before." (PMID 33932112, 2021). "The Cancer Genome Atlas (TCGA) dataset analysis revealed that CD276 mRNA levels are significantly higher in TNBC (and other breast cancer) tissues compared to normal breast tissue." (PMID 41462289, 2025). "CD276 (also known as B7-H3, Uniprot: Q5ZPR3), an immune checkpoint molecule that suppresses natural killer (NK) and T cells responses, is overexpressed in >80% of breast cancers, making it an attractive target for TNBC-specific therapy." (PMID 41462289, 2025). "Moreover, it has been reported that miR-665 directly target CD276 by associating with the CD276 3′-UTR region and mediated the downregulation of CD276 in breast cancer, which may provide a mechanism for miRNA to participate in the regulation of immune-related genes." (PMID 37371664, 2023). "CD276 (also known as B7-H3), shown here to be upregulated in VN-MCC compared to VP-MCC, is under ongoing investigation in other solid tumor malignancies, including prostate and breast cancer." (PMID 41228301, 2025). "While CD276 is commonly overexpressed in ESCC, it has also been reported in a variety of other solid tumors such as head and neck squamous cell carcinoma, lung cancer, prostate cancer, and breast cancer." (PMID 38566988, 2024). "CD200 expression was found to have no strong correlation with the other immune checkpoints expressed by breast cancer cells, and neither was CD276 expression." (PMID 33932112, 2021). "miR-708-5p suppressed CD276 expression in breast cancer cell lines, but this study did not examine phenotypic changes of miR-708-5p administration." (PMID 29050362, 2017). "That suggested the infiltration of CD8+ T cells, dendritic cells, or M1 macrophages in breast cancer can signify prolonged patient survival, and that the expression of CD200 and CD276 in cancer stem cells could impair the tumoricidal function of CD8+ T cells, dendritic cells, and M1 macrophages." (PMID 33932112, 2021). "As breast cancers can be classified into basal/stem cell–enriched and luminal/differentiated cell‐enriched clusters, we used logistic regression to screen out gene signatures which indicate Wnt, TGF‐β, and Hedgehog signaling‐related CD200 and CD276 in breast cancer stem cells." (PMID 33932112, 2021). "However, more convincing evidence of CD200 and CD276 expressed in human breast cancer stem cells has not been provided." (PMID 33932112, 2021). "Moreover, survival analysis demonstrated that CD276 and NPR1 expression had a negative influence on OS and RFS of claudin-low subtype breast cancer." (PMID 36685583, 2022).
prostate carcinoma (102 papers, 2009 to 2026). A carcinoma that arises from epithelial cells of the prostate gland. "The protein B7-H3 encoded by CD276 has been verified to be highly expressed in various tumors including prostate cancer and non-small cell lung cancer." (PMID 36175880, 2022). "B7-H3 (CD276) is an immune checkpoint overexpressed in prostate cancer with minimal expression in normal tissues and associated with poor prognosis, making it an excellent therapy target." (PMID 36323882, 2022). "High expression of CD276 is strongly associated with prostate cancer metastasis, poor prognosis, and high mortality, which is regulated by androgen and TGF-β signaling pathways." (PMID 34367975, 2021). "It has been shown that exosomes released by irradiated prostate cancer cells are enriched in B7-H3 protein (CD276), which has been identified as a diagnostic marker." (PMID 32204455, 2020). "Moreover, CD276 is highly expressed in advanced prostate cancer and correlates with the altered loss of BRCA2 and ATM function, as well as low intratumoral TILs." (PMID 35892678, 2022). "For example, decitabine increases the expression of an emerging drug target in prostate cancer, the immune checkpoint antigen CD276/B7 homolog 3 (B7-H3)." (PMID 38914477, 2024). "Our group has previously demonstrated B7-H3 (CD276) to be significantly elevated in metastatic prostate cancers compared with primary prostate cancer." (PMID 38709075, 2024). "Fractionated irradiation also upregulates expression of the immune checkpoint B7-H3 (CD276) on prostate cancer stem cells, and B7-H3 CAR T cells have demonstrated a potent cytotoxicity in vitro and significantly improved antitumor efficacy in mice." (PMID 38727261, 2024). "Preclinically, CD276-targeted CAR T cells for prostate cancer had synergistic outcomes when combined with irradiation in vitro and in vivo." (PMID 37173782, 2023). "PTEN loss was also associated with the increased expression of the immunosuppressive molecules IDO1 and CD276 in prostate cancer tissue." (PMID 35892678, 2022). "It was initially reported that B7-H3 (CD276) protein levels had risen in exosomes derived from irradiated prostate cancer cells." (PMID 35071650, 2022). "Following miR-187 mimic/inhibitor or CD276 overexpression transfection, their actions in prostate cancer cell biological processes were analyzed." (PMID 36245088, 2022). "Studies have shown that CD276 CAR T-cells can reduce radiation resistance in prostate cancer by targeting prostate cancer stem cells." (PMID 36360316, 2022). "Immunohistochemistry results depicted that the positive rate of CD276 in prostate cancer tissues was 59.65%, while that in adjacent normal tissues was 14.04%." (PMID 36245088, 2022). "Collectively, this study demonstrated that BMSC-derived exosomal miR-187 restrained prostate cancer by reducing CD276/JAK3-STAT3-Slug axis." (PMID 36245088, 2022). "The current study pinpointed that hBMSC-exos overexpressing miR-187 inhibited prostate cancer through disruption of the targeting CD276-mediated JAK3-STAT3-Slug signaling pathway activation." (PMID 36245088, 2022). "In prostate cancer, CD276 is a useful biomarker to identify highly aggressive metastatic prostate cancer." (PMID 35892678, 2022). "Prostate cancer cells were then exposed to BMSC-exos that were treated with either miR-187 mimic/inhibitor or CD276 overexpression for pinpointing the in vitro and in vivo effects of exosomal miR-187." (PMID 36245088, 2022). "The prognostic effects of CD276 have also been demonstrated in clear cell renal cell carcinoma, prostate cancer, colorectal cancer, and NSCLC." (PMID 31998416, 2020). "Irradiated prostate cancer cells have been shown in vitro to produce exosomes with elevated levels of B7-H3 (CD276)." (PMID 29951375, 2018). "Interestingly, CD276, also known as B7-H3, is a new promising immunotherapy target in various cancers, including prostate cancer." (PMID 37686409, 2023).
prostate carcinoma (continued). "In addition, the protein expression level of CD276 was found to be the highest in head and neck cancer and prostate cancer, whereas it was lowest in carcinoid tumors, renal cancer and lymphoma." (PMID 36717836, 2023). "Additionally, immunoblotting results depicted that CD276 was highly expressed in prostate cancer cell lines relative to RWPE-1 cells, and the highest expression was found in PC-3 cells." (PMID 36245088, 2022). "The relationship between CD276 and miR-187 in prostate cancer was evaluated." (PMID 36245088, 2022). "miR-187 was poorly expressed while CD276 was significantly upregulated in prostate cancer." (PMID 36245088, 2022). "Studies on prostate cancer cells showed that IR was accompanied by an increased CD276 and Hsp72." (PMID 35735486, 2022). "It was noted in our work that miR-187 was repressed while CD276 was elevated in prostate cancer." (PMID 36245088, 2022). "Additionally, restoring miR-187 inhibited the prostate cancer cell malignant properties by targeting CD276." (PMID 36245088, 2022). "In addition, in the GSE30994 microarray dataset, CD276 was elevated in prostate cancer samples, which was also verified by the starBase Pan-Cancer Analysis Platform." (PMID 36245088, 2022). "However, relatively high CD276 expression has been detected in various tumor tissues at all stages, including breast, cervical, colorectal, and prostate cancer." (PMID 35052695, 2021). "B7-H3 (CD276), a member of the B7 immunoglobulin superfamily, is a type I transmembrane protein that is notably overexpressed in various solid tumors, including bladder cancer, prostate cancer, and melanoma, while exhibiting limited expression in normal tissues." (PMID 40087690, 2025). "Overall, miR-187 delivered by hBMSC-exos targeted CD276 and inhibited JAK3-STAT3-Slug signaling pathway activation, thereby repressing the malignant capacities of prostate cancer cells." (PMID 36245088, 2022). "Our results pinpointed that miR-187 was diminished in prostate cancer tissues and cells and blocked the JAK3-STAT3-Slug signaling pathway by targeting CD276." (PMID 36245088, 2022). "Hence, we speculated that miR-187 might affect prostate cancer via regulation of CD276." (PMID 36245088, 2022). "Conclusively, miR-187 delivered by hBMSC-exos targeted CD276 and inhibited JAK3-STAT3-Slug signaling pathway, thus retarding the growth and metastasis of prostate cancer cells in nude mice." (PMID 36245088, 2022). "Collectively, miR-187 can decrease CD276 expression to inhibit the JAK3-STAT3-Slug signaling pathway, thus delaying the malignant phenotypes of prostate cancer cells." (PMID 36245088, 2022). "Therefore, CD276 may be an actionable target for the treatment of this subgroup of prostate cancer." (PMID 35892678, 2022). "One family member, B7-H3 (CD276), is overexpressed in several tumour types, including non-small-cell lung cancer (NSCLC), ovarian, and prostate cancer, and its expression is associated with poor treatment outcomes and survival." (PMID 37444640, 2023). "An increased level of exosomal CD276 was observed in the irradiated and senescent 22RV1 prostate cancer cell line, suggesting that this marker may provide a non-invasive way to monitor the efficacy of RT for prostate cancer patients." (PMID 31555599, 2019).